ANG (angiogenin)
Diseases named in the same sentence as ANG in open-access papers (continued):
Sharing a sentence is not in itself a finding about the gene and the disease.
tumor (continued). "Thus, in the present study, we employed Y2H and glutathione-S-transferase (GST) pull-down assay to further identify the binding domains and sites of these two proteins, respectively, and evaluated the function of ANG/ACTN2 interaction in tumor cell proliferation and motility." (PMID 35463945, 2022). "Moreover, TAMs might induce elevated angiogenin expression in the tumor microenvironment, leading to increased angiogenesis, which constitutes a critical factor for tumor growth and metastasis." (PMID 32987848, 2020). "We next tested whether TGFBR3-mediated tumor-suppressive function depends on ANG." (PMID 32471132, 2020). "On the basis of those previous reports, we speculated that hRNase5/ANG in some patients may be induced by hypoxic stress or proinflammatory cytokines derived from inflammatory cells, e.g., infiltrating macrophages, in the tumor microenvironment." (PMID 30449278, 2018). "Angiogenin may bind with follistatin, another angiogenic protein that in an in vivo model was found to increase the number of tumor associated capillaries but not tumor size." (PMID 21609465, 2011). "Exosomes contain or activate cytokines, including angiogenin, fibroblast growth factor (FGF), and vascular endothelial growth factor (VEGF), to promote tumor blood vessel formation, with FGF and VEGF exerting synergistic effects 230,231." (PMID 39744442, 2025). "NDs with a higher sp3/sp2 carbon ratio effectively reduce the proangiogenic activity of tumor cells by downregulating key cytokines such as IL-6, IL-8, TIMP-1, TIMP-2, ANG, and ANGPTs." (PMID 40804455, 2025). "Angiogenin, ANG, is known to be secreted by human PCa and contributes to cancer progression through mediating tumor angiogenesis, cancer cell survival, and proliferation." (PMID 38589887, 2024). "METTL21A plays a role in protein modification pathways, while ANG and VEGFA are essential for vascular endothelial cell function, with implications for conditions like ALS and tumor angiogenesis." (PMID 38681774, 2023). "MSC-secreted factors known to activate tumor cell growth and proliferation of other cancer entities are, for example, CCL2/MCP-1, angiogenin, and VEGF." (PMID 37781195, 2023). "Angiogenin (ANG), a member of the RNase A superfamily, has been demonstrated to promote tumour angiogenesis and metastasis in BC by activating key downstream target molecules of the PI3K-AKT-mTOR signalling pathway." (PMID 37052868, 2023). "Among the identified interactions, we suggest EDN1/EDNRB as a putative novel tumor/endothelial cell interaction, and ANG/PLXNB2 and ANG/EGFR as putative new autocrine loops in ccRCC cancer cells." (PMID 38025776, 2023). "To explore the mechanism by which fructose-cultured tumor cells regulate angiogenesis, we determined the levels of various pro-angiogenic factors, such as VEGF, bFGF, ANG and PDGF, in tumor cells under different culture conditions." (PMID 37507736, 2023). "Deletion of the IL30 gene in PC cells inhibits endothelial expression of IGF1, EDN1, ANG and CXCL10 and substantially impairs tumor angiogenesis." (PMID 38087324, 2023). "In one study, analysis of the “secretory phenotype” of tumor cells with activated EMT signaling revealed a distinct set of pro-inflammatory soluble factors, including IL-6, IL-8, GRO, GM-CSF, VEGF, and angiogenin." (PMID 36959556, 2023). "Moreover, ANG is supposed to play an essential role in a series of malignant phenotypes, including angiogenesis, proliferation, migration, invasion, metastatsis, recurrence, epithelial-mesenchymal transition (EMT), radiochemotherapy resistance, and tumor-associated immunity." (PMID 37928479, 2023). "Several studies have shown that overexpression of angiogenic factors such as PD-ECGF, bFGF, TGF-β, angiogenin, and COX-2 in different cancers are correlated with the advanced tumor stage and decrease patient survival." (PMID 35681234, 2022).
tumor (continued). "Neomycin and neamine, two drugs blocking the nuclear translocation of angiogenin (ANG), have been proven to inhibit tumour growth in vivo." (PMID 36499606, 2022). "In this study, we identified the binding domains and sites in ANG and ACTN2 and evaluated the function of this interaction in tumor cell behaviors." (PMID 35463945, 2022). "While CD4+ memory resting T cells contribute most T-cells within the tumour microenvironment (TME), their presence is highly influenced by CCL2, ANG, CHI3L1, IL-6 and IL-8." (PMID 36430641, 2022). "When the segment ACTN2 383–632 is overloaded, the functions of ANG and ACTN2 would be disrupted, such as cell proliferation, survival, and migration, which results in angiogenesis or tumor growth inhibition." (PMID 35463945, 2022). "It is noteworthy that while plasma level of ANG was also correlated with surgical and clinical stages, it was not correlated with biopsy grade and surgical Gleason scores, indicating that ANG is associated with aggressiveness of the tumor but not with their differentiation stage." (PMID 35752711, 2022). "Periodontal inflammation has been shown to induce epithelial–mesenchymal transition, which is an important element of tumor invasiveness as well as secretion of the angiogenic factors VEGF and angiogenin." (PMID 34299675, 2021). "Pre-analysis centrifugation of samples spiked with the T24 tumor cell line reduced levels of MMP9, SDC1, PAI1, ApoE, and ANG." (PMID 34204951, 2021). "Further, the inhibitor of ANG, RNH1 has been shown to prevent tumor-induced angiogenesis and tumor growth." (PMID 33525475, 2021). "In non-tumour d-SH-SY5Y cells, only the treatment with AuNP functionalized with ANG, both in the absence and in presence of copper, induced an increase of the VEGF mRNA transcription in comparison to the respective control (free ANG)." (PMID 31500197, 2019). "Compared to the expression levels in normal tissue, other genes, such as ADRB3, BTG2, DUSP4, RAD51 or FBLX7, were downregulated in specific tumor types, and ANG, ESD and STL7 were downregulated in most tumor types." (PMID 31159852, 2019). "Angiogenin (ANG), a member of RNase A superfamily, is recently demonstrated to promote tumor angiogenesis, tumorigenesis and metastasis of BCa by activating key downstream target molecules of PI3K-AKT-mTOR signaling pathway." (PMID 29190997, 2017). "Of the fifty-five angiogenic factors evaluated, about half including angiogenin, endoglin and most specifically VEGF, a prime HIF-1α regulated growth factor, were down regulated in the shhnRNP A18 tumor as compared to control." (PMID 26824423, 2016). "Much like its fungal counterpart, it inhibited angiogenin-, bFGF-and VEGF-induced tube formation and significantly inhibited LS174T tumor formation in athymic mice." (PMID 27014725, 2016). "More specifically, increased serum concentrations of angiogenin, VEGF, bFGF and IL-8 positively correlate with disease stage, tumor burden and overall survival rates." (PMID 27014725, 2016). "LANA has been reported to interact with the 14-kDa multifunctional protein angiogenin (ANG), which is considered to play a critical role in establishment of KSHV latency, anti-apoptosis and tumor angiogenesis." (PMID 25514370, 2014). "Tumor angiogenesis requires both upregulation of angiogenic stimulators such as VEGF, bFGF, angiogenin and downregulation of endogenous angiogenic inhibitors such as tumstatin, endostatin and thrombospondin." (PMID 24002681, 2013). "During tumor angiogenesis, angiogenic factors (e.g., vascular endothelial cell growth factor (VEGF), fibroblast growth factor-2 (FGF-2), angiogenin, or angiopoietins) and their receptors are produced by tumor cells and endothelial cells (ECs)." (PMID 24180549, 2013).
tumor (continued). "Regarding the other markers, we observed a trend towards a benefit from docetaxel in patients whose tumor was positive for CK14, Angiogenin, and β-Catenin, with a statistically borderline interaction, which deserves further analysis in larger series." (PMID 22044691, 2011). "Also, we verified that all the patients’ ascites EVs displayed EV-positive markers of CD63 and PDCD6IP (ALIX) proteins and tumour metastasis markers of N-cadherin (CDH2), claudin-1 (CLDN1) and angiogenin (ANG)." (PMID 40993350, 2025). "Indeed, extracellular vesicles can contain as cargo a variety of angiogenic factors, such as ANG, IL-6, IL-8 and VEGF, or even mRNA, which can be incorporated by cells of the tumor microenvironment, changing their behavior." (PMID 37762073, 2023). "The data obtained from these tumours are also consistent with an upregulation of anti-angiogenic ING4 mRNA levels in the human xenograft tumours in vivo, with no significant changes are detected for ANG, VEGFA, HIF1α, THBS2 and COL18A1." (PMID 35513564, 2022). "The expression of RNASE2 and LARP6 was slightly elevated in tumor tissue, and ANG was not collected in the Human Protein Profiles." (PMID 33589575, 2021). "Angiogenin (ANG) is a 14 kDa molecular weight extracellular protein, a member of the ribonuclease (RNase) superfamily of enzymes (also known as RNase 5); it was initially identified in a medium conditioned with tumor cells." (PMID 34356982, 2021). "Importantly, we found that ANG and PLXNB2 knockdown resulted in a faster exhaustion of the in vivo tumor-initiating ability of CSCs as assessed by the relative tumor growth rate between passages one and three." (PMID 31942000, 2020). "Furthermore, neomycin administration reduced tumor growth of HepG2-LX2 cells co-injected into mice, suggesting that angiogenin secretion by HCC cells favors tumor development via induction of HSC activation and ECM remodeling." (PMID 32850829, 2020). "Coordinated interplay of ANG and VEGF isoforms regulates tumor angiogenesis." (PMID 28744448, 2017). "In addition, it binds to G-protein-coupled receptors on tumour cells to induce the production of pro-angiogenic factors, including vascular endothelial growth factor (VEGF) and angiogenin (ANG)." (PMID 24203995, 2013). "Serum angiogenin concentrations were not in a correlation with any of tumour features or inflammatory markers." (PMID 23412843, 2012). "Tumor angiogenesis occurs under the influence of fibroblast growth factor (FGF), epidermal growth factor (EGF), vascular endothelial growth factor (VEGF), placental growth factor (PLGF),tumor necrosis factor-alpha (TNFa), platelet-derived growth factor (PDGF) and angiogenin (Ang)." (PMID 35717207, 2022). "The tumor size of the control groups (PBS, WT phage, fd388‐RS′‐WV phage, and fd388‐AR‐RS phage groups) were significantly bigger than that of the fd388‐AR‐WV‐treated group, indicating that tumor‐homing angiogenin selectively inhibited new vessel formation of disease tissues." (PMID 35246962, 2022). "Serum ANG levels are not elevated in patients with HCC compared with those in healthy controls; however, higher serum ANG levels are significantly associated with HCC histological grades, tumor vascularity, and tumor size." (PMID 29736193, 2018). "Interestingly, CM derived from HuH7, PT-7, PT-12 and PT-19 showed high levels of IL-6 and angiogenin while the CM from the HC-PT-5 tumor did not present these cytokines." (PMID 29113298, 2017). "Angiogenesis factors may promote tumor growth; VEGF and angiogenin levels are low in ACCS." (PMID 18461121, 2008). "In addition, activation of MMPs can be induced by several secreted growth factors, including VEGF, FGF, TGF-α and -β, and angiogenin, that can be secreted in an autocrine manner by tumor cells or in a paracrine manner from nonmalignant cells present in the TME." (PMID 36980704, 2023).
tumor (continued). "Only VEGF was more expressed by CD49a+Eomes+ cells in nontumorous liver tissue, while in the tumor, CD49a+Eomes+ cells expressed higher levels of VEGF, PlGF, IL-8, MMP-9, angiogenin, and CXCL10 (IP-10)." (PMID 33802077, 2021).
cancer (109 papers, 2007 to 2026). A tumor composed of atypical neoplastic, often pleomorphic cells that invade other tissues. "Angiogenin, a secreted ribonuclease, is highly expressed in the liver, and previous work has implicated this protein in the pathophysiology of cancer, neurological disorders, and cardiovascular diseases." (PMID 38626182, 2025). "In contrast and based on our results, low levels of angiogenin were associated with increased cancer-associated survival in BL cohort treated with nab-paclitaxel and gemcitabine." (PMID 36497475, 2022). "Further, serum angiogenin levels are associated with different disease conditions, including cancer, cardiovascular, and inflammatory bowel diseases." (PMID 36466652, 2022). "In conclusion, these results support the clinical utility of RAS gene SNPs AT2R rs11091046, REN rs12750834, and ANG rs699 in the genetic cancer risk assessment of patients and families with BC." (PMID 34898568, 2021). "In summary, this candidate gene association study supports the clinical utility of the RAS gene SNPs AT2R rs11091046, REN rs12750834, and ANG rs699 in the genetic cancer risk assessment of patients and families with BC." (PMID 34898568, 2021). "Some suggest nuclear translocation of ANG to induce rRNA production, while others claim tRNA cleavage by ANG in cytoplasm, is a cause for uncontrolled proliferation and cancer." (PMID 33525475, 2021). "Angiogenin has been widely associated with angiogenesis in cancer disease, participating in cell proliferation, migration, and invasion of endothelial cells." (PMID 30008694, 2018). "Angiogenin, an RNase A associated with cancer, exhibited a kcat/Km of 3.3 × 107M−1·s−1, similar to the value for RNase A. This probe was used in an inhibition assay with 3′-UMP and 5′-ADP." (PMID 25019631, 2014). "Finally, low levels of angiogenin were significantly associated with longer cancer-associated death time (HR = 0.44; 95% CI: 0.17–1.10; p = 0.038)." (PMID 36497475, 2022). "Initially characterized as functional sncRNAs mainly in the context of cell cycle propagation and proliferation in cancer cells, subsequent studies have linked tsRNAs, and in particular angiogenin-processed ones, to important roles in neuron survival and neuro-developmental disorders." (PMID 34882524, 2021). "In mammalian cells, they are generated from angiogenin (ANG)-mediated anticodon cleavage of tRNAs and have been shown to regulate translation, promote stress response, promote cell proliferation, and be associated with cancers, neurodegenerative diseases, and metabolic disorders." (PMID 33332353, 2020). "Moreover, serum ANG levels are also associated with cancer progression." (PMID 29736193, 2018). "VEGF proteins were particularly abundant in all cancer and endothelial cell secretomes, whereas ANG and ANGPT2/ANGPTL4 in SK-OV-3, suggesting a potentially significant role in the formation of the HBEC-5i/SK-OV-3 networked constructs." (PMID 41279931, 2025). "Biologically, RNH1 participates in processes such as angiogenin (RNase 5)-regulated neovascularization, monitoring of the cellular oxidative state, and cancer growth and metastasis." (PMID 38951571, 2024). "The abundance of tRH of nuclear genome origin is positively correlated (Spearman’s rho = 0.67–0.87) with angiogenin mRNA/protein abundance in non-cancer liver tissue." (PMID 36901804, 2023). "We thus downregulated the expression of angiogenin in four ccRCC cell lines, 786-O, Caki1, Caki2, and A498 using siRNA to investigate the biological functions of angiogenin in cancer cells." (PMID 38025776, 2023). "We then investigated how angiogenin silencing would impact the secretion of soluble factors expressed by cancer cells." (PMID 38025776, 2023). "Our results thus suggest that angiogenin enhances cancer cell proliferation and down-regulates the secretion of pro-inflammatory molecules." (PMID 38025776, 2023).
cancer (continued). "Angiogenin knock-down significantly impaired cancer cell proliferation on three out of the four cell lines tested." (PMID 38025776, 2023). "We identified 50 putative communication channels specifically used by cancer cells to interact with other cells, including two novel angiogenin-mediated interactions." (PMID 38025776, 2023). "Several in vivo studies have shown that ANG inhibitors and activators are effective therapeutics for cancer and ALS, respectively." (PMID 35955913, 2022). "In almost all cancers, ANG expression is increased, potentially in order to increase tRF expression and, in turn, cancer proliferation." (PMID 35721477, 2022). "A number of antiangiogenic drugs targeting VEGF/VEGFR (VEGF receptor) or ANG/Tie2, or both, are currently being used for cancer treatment, or are still in various stages of clinical development or preclinical evaluation." (PMID 35805939, 2022). "The prime role of angiogenin is angiogenesis that is required to promote growth and metastatic spread of cancer cells." (PMID 36466652, 2022). "Mechanistically, ZNF750 suppresses the expression of some cancer-related genes such as angiogenin, VEGF, RGS5, CD105, ITGA5, ITGB1, and CD44." (PMID 34288812, 2021). "Due to its well-known angiogenic character on cancer cells, we excluded angiogenin from our current research." (PMID 34359731, 2021). "Although most recent studies have focused on its potential as an anti-angiogenin based cure for cancer, it is also known for its antimicrobial activity and association with diverse inflammatory diseases and innate immunity." (PMID 31936482, 2020). "In this review, we focus on recent advances in the understanding of the ANG/TIE pathway in cancer and describe its potential as a therapeutic target to reinforce current antiangiogenic and immune checkpoint inhibitor (ICI) therapies for cancer treatment." (PMID 33217955, 2020). "Altogether, the evidence from various cancer types supports a positive regulation of hRNase5/ANG in tumorigenesis." (PMID 30449278, 2018). "Angiogenin is known as a pro-angiogenic growth factor that is up-regulated in several types of cancer." (PMID 30352093, 2018). "We also recommend the performance of large prospective multicenter studies and believe that multidisciplinary teams should collaborate to determine the clinical applicability of serum ANG levels as a biomarker for cancer." (PMID 29736193, 2018). "These tRFs, generated by certain tRNases including angiogenin, were found to be involved in cellular stress response and cancer progression by means of regulating transcription and translation in cells." (PMID 29563550, 2018). "Our pooled estimates indicated that serum ANG levels in patients with cancer were significantly higher than those in healthy controls (pooled SMD = 0.728, 95% CI = 0.484 to 0.973, p < 0.001)." (PMID 29736193, 2018). "Specifically, serum ANG levels in patients with cancer were 96.21 ng/ml (95% CI = 69.85 to 122.57) higher than those in corresponding healthy controls, according to the results of the pooled data analysis." (PMID 29736193, 2018). "ANG levels have been assessed in various types of cancer to establish the relationship between serum ANG levels and cancer progression." (PMID 29736193, 2018). "In this section, we will focus on the role of hRNase5/ANG in human diseases, especially on its functions in cancers." (PMID 30449278, 2018). "Subsequently, bovine pancreatic RNase A, bovine seminal RNase, Barnase, Ranpirnase (RNase I from Rana pipiens), human pancreatic RNase 1, human eosinophil-derived RNase (EDN) and angiogenin (Ang) all exhibit potent toxicity to cancer cells." (PMID 29510557, 2018).